ETS1 (ETS proto-oncogene 1, transcription factor)
Diseases named in the same sentence as ETS1 in open-access papers (continued):
Sharing a sentence is not in itself a finding about the gene and the disease.
cancer (continued). "In addition, there is no universal underlying mechanism of the action of fentanyl on cancer cells, and via either opioid receptor-dependent or -independent mechanisms such as inhibition of Ets-1 and HDAC5, and activation of wnt/β-catenin." (PMID 35999506, 2022). "Furthermore, the cluster mir-222/221 is implicated in both IR and cancer by targeting genes that are implicated in both MetS and cancer pathogenesis: transcription factor v-ets erythroblastosis virus E26 oncogene homolog 1 (ETS1), DICER, PTEN." (PMID 34199293, 2021). "ETS1 is associated with poor prognosis and therapy resistance in most of the cancers." (PMID 32824207, 2020). "Other targets of LRF/ZBTB7A-mediated regulation of oncogenesis include Striatin 4 (STRN4), a protein implicated in the progression of various human cancers and protein C-ets-1 (ETS-1), which is overexpressed in several cancers and implicated in cell proliferation, apoptosis, invasion, and migration." (PMID 31823818, 2019). "ETS1 is upregulated in cancer cells and is linked to poor clinical outcome in patients, so it may serve as a diagnostic marker." (PMID 31889958, 2019). "Interestingly, however, underlying mechanisms of transcriptional regulation of Ets1 gene expression is poorly characterized in cancer cells." (PMID 30467308, 2018). "ETS1 is implicated in the cell response to stress, and an increased expression of this factor regulates various metabolic and oxidative stress pathways in several cancer models but mediates vascular inflammation as well." (PMID 29296203, 2017). "Furthermore, current studies revealed the association of ETS‐1 expression with metabolism and oxidative stress in cancer cells." (PMID 28236660, 2017). "Thus, PARP-1-mediated PARylation is involved in a specific regulation of Ets-1 protein levels in cancer cells and we assume that this mechanism is linked to its proteasomal degradation." (PMID 23405229, 2013). "The TRA2B gene is a transcriptional target of the protooncogene ETS-1 which might cause higher levels of expression in some cancer cells which express this transcription factor." (PMID 23935626, 2013). "Indeed, there are many well-established target genes for Ets-1 that are closely linked to cancer progression, particularly mediators of extracellular matrix degradation, cancer cell migration and angiogenesis." (PMID 24280356, 2013). "The functional interaction analyses in this study further strengthen the importance of Ets-1 in regulating cancer metastasis due to the pathway associations we have observed in WNT, vascular endothelial growth factor, and MMP signaling, as well as ERK5, MAPK, EGF, PDGF, MET and GPCR pathways." (PMID 24280356, 2013). "Overall, data from such studies have often linked ETS1 expression to advanced state of epithelial cancers with poorer differentiation, higher invasive activity and angiogenesis, an increased risk to metastasis and a higher tendency to acquire drug resistance–all hallmark features of cancer." (PMID 31306413, 2019). "Furthermore, ETS1 expression in these patients was shown to significantly correlate with higher clinical stage with higher levels specifically associated with the late stages (III/IV) of cancer." (PMID 31306413, 2019). "Integration with our previous transcriptome data for KDM3A and ETS1 in the same cell lines confirmed regulatory control of genes related to cancer growth and metastasis." (PMID 39448867, 2025). "EGR2 has been shown to promote metastasis by regulating cell migration and the immune status of the microenvironment, whereas ETS1 enhances cancer cell invasiveness by activating EMT- and matrix remodeling-related genes." (PMID 41373733, 2025). "Leveraging drug screens, we discovered that ETS1-high cancers are vulnerable to HSP90 inhibitors (e.g., Alvespimycin), which suppress ETS1 by disrupting HIF1A-mediated transcriptional activation." (PMID 40777467, 2025).
cancer (continued). "Our previous work demonstrated that PARP‐1 inhibition by PJ‐34 induced cell death of Ets‐1‐expressing cancer cells." (PMID 39778077, 2025). "In a previous study, we revealed that poly(ADP‐ribose) polymerase‐1 (PARP‐1) inhibition by PJ‐34 results in Ets‐1 level increase in cells, which is related with cell death of Ets‐1‐expressing cancer cells." (PMID 39778077, 2025). "BRG1, the ATPase subunit of the BAF chromatin remodeling complex, has been shown to cooperate with KDM3A and ETS1 on chromatin, and to promote invasive and metastatic properties in other cancers." (PMID 39448867, 2025). "ETS1 has also been reported to regulate malignant tumor cell invasion and restrict poxvirus infection." (PMID 40198713, 2025). "Lastly, expression of ERK downstream effectors Ets-1 and Ets-2, known for their cancer promoting roles, was also reduced." (PMID 41209002, 2025). "Epigenetic modifications play a significant role in regulating Ets-1 expression, particularly in cancer, and polyphenols have been identified as potent epigenetic modulators." (PMID 39861471, 2025). "IHC confirmed the high expression of FGL1 in cancer tissues, whereas ChIP-qPCR and dual-luciferase reporter gene assays identified ETS1 as a transcription factor that mediates its high expression." (PMID 41024301, 2025). "Future clinical trials must focus on evaluating the safety, tolerability, and efficacy of ETS-1 inhibitors in humans to assess their potential as viable cancer therapeutics." (PMID 40181983, 2025). "This induced cell death of Ets‐1‐expressing cancer cells and an increase in DNA damage as detected by the level of γH2AX, a biomarker for DSBs." (PMID 39778077, 2025). "Many studies correlated the level of expression of the ETS1 protein with the occurrence of unfavorable factors of diverse carcinoma types, but the gained results are controversial." (PMID 39941022, 2025). "The study suggested that Gln deprivation results in the deactivation of the transcription factor ETS1, which is responsible for the expression of vimentin and metalloproteases, proteins involved in cancer cell migration and invasion." (PMID 38750263, 2024). "We explored how xanthohumol affects Ets-1 phosphorylation and degradation and provided insights into potential therapeutic approaches for cancers driven by Ets-1 dysregulation." (PMID 39468027, 2024). "RARα can bind to the Ets1 promoter and induce the expression of Ets1 mRNA and protein in cancer cells." (PMID 39055491, 2024). "Overexpression of lncRNA LINC00922 prevents SIRT3 recruitment to the ETS1 promoter and then increases ETS1 transcription by increasing H3K27cr level in this region, ultimately promoting cancer metastasis." (PMID 39606030, 2024). "SRSF5 is reported to promote cancer development and progression by regulating the splicing of multiple genes, including ETS1, METTL14, Mcl-1, Cyclin L2, and CCAR1." (PMID 38263157, 2024). "An increasing amount of studies have now reported that PARP-1 inhibition causes an important increase in DSB DNA damage in cancer cells expressing ETS transcription factors such as Erg, Fli1, or Ets-1." (PMID 37686260, 2023). "As a member of the ETS family, ETS1 is suspected to be an oncogene involved in various cancers and to have a vital function in haematopoietic cell development." (PMID 37326025, 2023). "Previous research has shown that B4GALT5 is regulated by Ets family transcription factors, including Ets-1 and Ets-2, in cancer cells." (PMID 37628686, 2023). "Strong positive correlation between ETS1 and the top 5 correlated genes was observed across cancers." (PMID 36760475, 2023). "ETS-1, a candidate ccRCC master TF known to have a role in cancer pathogenesis as well as angiogenesis and hematopoietic stem cell differentiation, is another example." (PMID 36681680, 2023). "SNHG6 binds to miR-944 and miR-181d-5p leading to an increase in ETS1 expression eventually accelerating cancer cell proliferation, EMT, and inhibiting apoptosis." (PMID 37735423, 2023).
cancer (continued). "Remarkably, in the context of cancer, ETS1 has emerged as a pivotal player, fostering tumor advancement and metastasis through its regulation of genes pivotal to cell invasion, angiogenesis, and the intricate orchestration of EMT." (PMID 38124072, 2023). "THYM showed unique correlation between immune checkpoint genes and ETS1 expression compared with other types of cancers." (PMID 36760475, 2023). "We performed a pan-cancer integrated bioinformatic analysis to explore the prognostic potential and immune features of ETS1 and ETS2 across cancers." (PMID 36760475, 2023). "Pan-cancer analysis of the expression of ETS family showed that ETS1 was upregulated in 12 and downregulated in 6 types of cancers." (PMID 36760475, 2023). "ETS1 expression and activity were inconsistent in several cancers (PAAD, THYM, CHOL, DLBC, TGCT, and THCA)." (PMID 35463077, 2022). "As a whole, the ETS1, TNRC6B, and TNRC6C genes were thought to be preventive against tumors, while the remaining SRGs appeared linked to cancer risk." (PMID 35911954, 2022). "Ets-1 is known to promote cancer progression via its involvement in proliferation, EMT, invasion, angiogenesis, and drug resistance." (PMID 35789155, 2022). "In conclusion, our findings revealed a close relationship and prognostic significance of ETS1 expression in various human cancers." (PMID 35463077, 2022). "E26 transformation–specific-1 (Ets-1) is one such oncogenic TF, reported to contribute to the development and progression of a variety of cancers through transactivation or repression of various target genes." (PMID 35789155, 2022). "Nowadays, ETS1 is becoming increasingly popular as a possible biomarker and essential mediator in various cancers." (PMID 35463077, 2022). "The goal of this study is to investigate the relationship between ETS1 and immunology and to determine its predictive value as a possible biomarker in human cancers." (PMID 35463077, 2022). "Ets1 belongs to the large family of the ETS domain family of transcription factors and is associated with poor prognosis in most cancers." (PMID 36189255, 2022). "Several investigations have found that ETS1 can hinder cell differentiation in a variety of circumstances and increase its cancer-promoting activity by keeping cells immature and proliferating." (PMID 35463077, 2022). "We further analyzed the potential co-expression of EIF4EBP1 and either ETS1 or MYBL2 at the mRNA level in multiple different cancer types using datasets available in R2 AMC." (PMID 35228525, 2022). "Similar findings were obtained when cancer cells were co-transfected with wild-type ETS1 and the shGSK3β vector." (PMID 34023818, 2021). "In cancer cells expressing Ets-1, Cas9/VP64 and sgRNA continue to drive their self-expression, and then transcriptionally activate luciferase or GFP." (PMID 34124154, 2021). "MMP-9 induction was less prominent in ETS1-3A-overexpressing cancer as compared with that observed when ETS1 was overexpressed." (PMID 34023818, 2021). "ETS1 has been found to be overexpressed in several solid tumors, including breast, colorectal, endometrial, lung, and ovarian cancers." (PMID 34023818, 2021). "The pro-oncogene ETS-1 (E26 transformation-specific sequence 1) is a key regulator of the proliferation and invasion of cancer cells." (PMID 34858853, 2021). "ETS1 can inhibit cell differentiation in many different situations and promote its cancer-promoting effect by keeping cells in a state of immaturity and proliferation." (PMID 34686186, 2021). "In the future, prospective studies of ETS1 and TCF4 expression and their role in immune invasion of human cancers are needed, and a novel antitumor immunotherapeutic agent targeting ETS1 and TCF4 is successfully developed and tested." (PMID 34686186, 2021). "It seems that these differential ETS1 regulation strategies are due to the activation of separate pathways in these cell lines, which maintain their cancer phenotype and invasive potential." (PMID 34136678, 2021).
cancer (continued). "ETS1 belongs to a large family of the ETS domain family of transcription factors and is thought to be linked to poor survival during cancer progression as well as transcription networks associated with CD8 T cell differentiation." (PMID 34504794, 2021). "When EHF-SF was overexpressed in MDA-MB-231 cells, the cell morphology was altered from spindle-like to cobblestone-like shapes, a change that was accompanied by repression of ZEB1 and ETS1 as well as in vitro cell migration and anti-cancer drug resistance." (PMID 33712555, 2021). "To confirm the role of GSK3β in promoting MMP-9 expression, we examined its induction in cancer cells co-transfected with the ETS1 expression vector and GSK3β siRNA." (PMID 34023818, 2021). "A more interesting idea is to use CRISPReader to sense Ets-1 and to develop a broad-spectrum anti-cancer tool." (PMID 34124154, 2021). "When stabilized and activated by kinases, ETS1 promotes cancer cell invasiveness by inducing the expression of matrix metalloproteinases (MMPs)." (PMID 34023818, 2021). "The transcription factor ETS-1 (E26 transformation-specific sequence 1) is an important regulator of malignant tumor cell proliferation that also has central roles in metastasis and invasion." (PMID 34858853, 2021). "This study fully confirmed the effectiveness of Ets-1 as a broad-spectrum cancer related signal and provided a new anti-cancer tool based on the CRISPReader system." (PMID 34124154, 2021). "Previous studies have shown that ETS-1 is a crucial SRC effector protein that regulates cancer cell proliferation, anti-apoptosis, and metastasis." (PMID 32435511, 2020). "Among 10 CpG sites in locus #1, methylation status of cg26559804, cg26503877, and cg11588197 showed significant inverse correlation with ETS1 expression in multiple types of cancers." (PMID 32477936, 2020). "ETS1 also acts as a key regulator of MMPs such as MMP1, MMP3, and MMP9 in human cancer-associated fibroblasts (CAFs)." (PMID 32855630, 2020). "The transcription factor ETS-1 plays an important role in several cancers, including breast, lung, and head-and-neck." (PMID 32435511, 2020). "Despite the established oncogenic function of ETS1 in human cancers, recent studies have proposed contrasting roles of ETS1 as anti-oncogenes suggesting dichotomous roles of ETS1 for tumorigenesis in context-dependent manner." (PMID 32477936, 2020). "AIRE is upregulated in OSCC and promotes the expression of cancer-related genes, at least in part by functional interaction with ETS1." (PMID 32012175, 2020). "The function of ETS1 impacts cancer cell viability resulting from reduced levels of glucose uptake and ATP production based on studies in ETS1 knockouts mice." (PMID 32194642, 2020). "KDM3A transcriptome analysis revealed, in addition to Ets1 and MCAM, other genes previously implicated in the promotion of aggressive cancer properties, including the genes FYN, AXL, LOXL2 and PLAU." (PMID 32577157, 2020). "In this context, our result proposed potential therapeutic approach targeting cis-regulatory elements of ETS1 to modulate the overall level in cancer cells." (PMID 32477936, 2020). "For other genes that are not included in the Sanger database, we also confirm their important role in cancer-related biological processes through literature verification, such as ETS1 and RHOA in hallmark “Activating Invasion and Metastasis”." (PMID 32117445, 2020). "ETS1 also facilitated the acquisition of invasiveness, drug resistance and neo-angiogenesis in cancer cells." (PMID 31889958, 2019). "We found that ETS1 preferentially binds cancer specific regulator elements, in particular Super-Enhancers of key EMT genes, highlighting its role as a master regulator." (PMID 31306413, 2019).
cancer (continued). "Our results also show that ETS1 is degraded by the NHLRC1-induced ubiquitination in early stage to allow cancer cells to maintain in early stage by inhibiting invasive functions, such as cell migration and ECM remodeling." (PMID 31217907, 2019). "This cohort of DEGs that were exclusive to the siRNA-mediated knockdown of ETS1 were involved in PI3K signaling, as well as processes that have been associated with EMT in cancer such as inflammation and FGF signaling." (PMID 31306413, 2019). "The MDA-MB-231 cells were used as a model of invasive cancer cells in which high levels of expression of Ets-1 are measured, while MCF-7 cells are non-invasive cells that show low levels of expression of Ets-1." (PMID 30857266, 2019). "Previous studies reported that the MEK/ERK pathway regulated ETS-1 through ERK phosphorylation of ETS-1 threonine 38 (T38) in many types of cancers." (PMID 31118072, 2019). "Taken together, these observations strongly suggest that the increase in MED28 expression by E2F-1, ETS-1, C/EBPβ, and NRF-1 is associated with cancer progression and poor prognosis." (PMID 30970566, 2019). "We further validated ETS1/TGF-β link by examining the enrichment of ETS1 direct targets in established gene-signatures related to TGF-β activation in cancer." (PMID 31306413, 2019). "Incessant telomere synthesis in cancer cells depends on specific mutations in the TERT promoter, enabling its activation by transcription factors ETS1 and p52." (PMID 30093619, 2018). "Under such conditions, several transcription factors (such as AP-1, Ets1, and hypoxia-mediated HIF1α [HIF1α]) are known to directly upregulate Ets1 transcription in cancer cells." (PMID 30467308, 2018). "The ETS proto-oncogene 1 (Ets1) has versatile roles during the cellular processes of cancer development." (PMID 30467308, 2018). "Considering that miR-125b targets a wide spectrum of genes including PTGS2 and ETS1, and that miRNAs are proposed as tools for cancer therapy, we tested miR-125b alone or in combination with NS-398, a specific chemical inhibitor of PTGS228." (PMID 29700305, 2018). "Based on Ets1 level, cancer cells were divided into two categories: Ets1high and Ets1low cell lines." (PMID 30467308, 2018). "We found that metastatic MDA-MB-231 (Ets1high) cancer cells have active chromatin status in the Ets1 locus compared to less metastatic MCF-7 (Ets1low) cells." (PMID 30467308, 2018). "This further predicts a non‐migratory shift, which supports the fact that inactivation of ETS‐1 can prevent cancer progression." (PMID 28236660, 2017). "Chemical targeting of ETS1 for proteolysis would be among the few curative strategies in cancer therapeutics." (PMID 28474232, 2017). "The HGF/c-Met/ETS-1 pathway mediates the proliferation, development, metastasis, invasion, and angiogenesis of a multitude of human cancer cells." (PMID 29312607, 2017). "In contrast, inhibition of ETS-1 can reduce the proliferation and invasion of cancer cells and prolong the survival of in vivo models." (PMID 26826553, 2016). "ETS-1 plays important roles in cell proliferation, angiogenesis, and apoptosis; it also regulates the invasion, recurrence and metastasis of cancers by altering cell adhesion and promoting matrix proteolysis." (PMID 26826553, 2016). "These genes included ANKLD1, AXL, CAV1/2, LDHB, ETS1, IFI16, PTRF (cavin), KIAA1199 and VIM, which have previously been linked to drug resistance in breast and other cancers." (PMID 26646320, 2016). "ETS1 plays an important role in cancer progression due to its ability to activate the transcription of metastasis-, angiogenesis- and invasion-associated genes." (PMID 27449293, 2016). "Our results provide evidence of an Rb1-dependent Ets1-Zeb1 amplification loop that is important in both cancer and in normal development of the thymus." (PMID 25880398, 2015). "ETS-1 has gained attention in cancer research for its importance in cell migration, invasion and proliferation." (PMID 25421630, 2015).